OR1A2 (olfactory receptor family 1 subfamily A member 2)
Description:
Odorant receptor.
Synonyms: OR17-6
Tractability: Antibody: UniProt places it where antibodies can reach, with medium confidence; UniProt predicts a signal peptide or a membrane-spanning region; its Gene Ontology location is reachable by antibodies, with medium confidence.
Gene: Protein-coding gene on chromosome 17 (3,197,519 to 3,198,448, forward strand). Ensembl gene ENSG00000172150.
Subcellular location: Cell membrane
Pathways (Reactome):
Sensory Perception: Expression and translocation of olfactory receptors
Gene Ontology:
Molecular function: G protein-coupled olfactory receptor activity; olfactory receptor activity; G protein-coupled receptor activity
Biological process: positive regulation of cytokinesis; signal transduction; detection of chemical stimulus involved in sensory perception of smell; G protein-coupled receptor signaling pathway
Cellular component: plasma membrane; membrane
Genetic constraint (gnomAD): Loss-of-function variants: 1 observed, 3.27 expected, observed/expected ratio (o/e) 0.31, 90% interval 0.11 to 1.38. That is too few expected variants to judge how well the gene tolerates losing a copy. Missense variants: 353 observed, 380.54 expected, observed/expected ratio (o/e) 0.93, 90% interval 0.85 to 1.01. Synonymous variants: 131 observed, 143.87 expected, observed/expected ratio (o/e) 0.91, 90% interval 0.79 to 1.05.
Homologues: Orthologues: dog OR1A1 (79% identical), mouse Or1a1b (77% identical), mouse Or1a1 (77% identical), rat Or1a1b (76% identical), rat Or1a1 (74% identical). Paralogues in human: OR1A1 (83% identical), OR1F1 (50% identical), OR1N1 (50% identical), OR1N2 (50% identical), OR1G1 (50% identical), OR1J2 (49% identical), OR1J4 (49% identical), OR1L4 (49% identical), OR1L6 (49% identical), OR1E1 (49% identical), OR1L1 (49% identical), OR1E2 (48% identical), and 116 more.
Diseases named in the same sentence as OR1A2 in open-access papers:
OR1A2 is named in the same sentence as 4 diseases in open-access papers, as found by Europe PMC text mining. Sharing a sentence is not in itself a finding about the gene and the disease. The quoted sentences say what the papers report.
hepatocellular carcinoma (3 papers, 2015 to 2021). A malignant tumor that arises from hepatocytes. "OR1A2 is an ectopically expressed receptor with only 13 known ligands, implicated in reducing hepatocellular carcinoma progression, with enormous therapeutic potential." (PMID 34235481, 2020). "In hepatocellular carcinoma, OR1A2, which is activated by monoterpene–Citronellol, reduced cell proliferation." (PMID 33566867, 2021). "OR1A2 has been heterologously expressed and identified at the protein level in Huh7 cells, a model system for hepatocellular carcinoma, where the activation of OR1A2 by (S)-(−)-citronellal leads to calcium signalling and reduction in cell proliferation." (PMID 34235481, 2020). "Activation of OR1A2 (olfactory receptor, family 1, subfamily A, member 2) was indicated in hepatocellular carcinoma progression with significant phosphorylation of p38 MAPK and reduced cell proliferation." (PMID 26315111, 2015).
liver cancer (1 paper, 2024). An epithelial or non-epithelial malignant neoplasm that arises from the liver. "For example, in a liver cancer cell line, OR1A2 signaling was reported to influence proliferation." (PMID 38965271, 2024).
cancer (1 paper, 2025). A tumor composed of atypical neoplastic, often pleomorphic cells that invade other tissues. "In our study, we selected six human olfactory receptors including OR51E2, OR52cs, TAAR9, OR51E1, OR1A1, and OR1A2 that have been linked with research for the possible development of cancer treatment and detection methods." (PMID 39944883, 2025).
OR1A2 also shares sentences with these, for which no sentence is quoted: prostate carcinoma (1 paper).